KDM6A (lysine demethylase 6A)
Diseases named in the same sentence as KDM6A in open-access papers (continued):
Sharing a sentence is not in itself a finding about the gene and the disease.
bladder cancer (continued). "Notably, this sex disparity in cancer incidence highlights KDM6A’s role in protecting females from bladder cancer through X chromosome maintenance and epigenetic mechanisms." (PMID 39731171, 2024). "In normal bladders, it is possible that high KDM6A expression due to female chromosomal sex may protect women from developing bladder cancer as frequently as men." (PMID 37666817, 2023). "Genetic alterations of KDM6A may be clinically actionable and related to the malignant progression of bladder cancer." (PMID 36052737, 2022). "Studies have suggested loss of KDM6A may amplify PRC2 complex mediated gene repression and dependency in bladder cancer cells that can be sensitized to EZH2 inhibitors." (PMID 34220955, 2021). "This was consistent with the clinical observation that mutations or reduced expression of KDM6A is associated with worse disease-free survival in female patients with bladder cancer but not in male patients." (PMID 33330090, 2020). "Since KDM6A connects KMT2D and RB1 mutations we hypothesize that there is a biological pathway that unites the impact of these three mutated genes and is important for the biologic fitness of bladder cancer cells." (PMID 35073341, 2022). "However, the role and detailed molecular mechanism of KDM6A involved in bladder cancer progression remains unknown." (PMID 34006303, 2021). "However, when the cohort was expanded to 125 cases, cumulative mutations in KDM6A were no longer elevated in bladder cancer samples so this gene was not used for construction of the diagnostic panel." (PMID 31938901, 2020). "The used data were for the wild-type KDM6A-expressing UMUC-1 luminal bladder cancer cell line, on which we performed ectopic expression of wild-type KDM6A on UMUC-1 cells, which is normally a KDM6A mutant and lacks KDM6A expression." (PMID 36980177, 2023). "FOXA1 has been documented to bind to the promoter of KDM6A and PLOD2, thus promoting their transcription in bladder cancer and non-small-cell lung cancer, respectively." (PMID 35498155, 2022). "In a murine model of bladder cancer, which occurs in 4 times as many males as females, knockout of Kdm6a decreased survival in female, but not male mice." (PMID 38949020, 2024). "We performed KDM6A ChIP-seq for three different cell lines: BdEC (normal primary bladder epithelial cells), SV-HUC-1 (immortalized bladder epithelial cells), and T24 (the muscle-invasive bladder cancer cell line)." (PMID 36980177, 2023). "Beyond KDM6A, other genes involved in epigenetic regulation, including KMT2C (Lysine N-methyltransferase 2C), KMT2D (Lysine N-methyltransferase 2D), and ARID1A (AT-rich interactive domain-containing protein 1A), also display aberrant expression patterns in bladder cancer." (PMID 40600050, 2025). "Interestingly, in almost 50% of bladder cancer cases there is a significant genetic aberration in chromatin remodeling genes, such as KMT2C (19.7%), KMT2D (28.3%), NCOR1, EP300 (16%), and CREBBP (13.3%) along with KDM6A." (PMID 33003334, 2020).
breast cancer (48 papers, 2014 to 2026). A primary or metastatic malignant neoplasm involving the breast. "Conversely, there is evidence that overexpression and upregulation of KDM6A are associated with poor prognosis in breast cancer and clear cell RCC." (PMID 37924117, 2023). "The function of KDM6A (UTX), an H3K27me3-demethylase, is associated with luminal breast cancer cell proliferation and metastasis." (PMID 35453496, 2022). "The loss of KDM6A in human breast cancer cells causes a decrease in estrogen-induced cell proliferation in vitro." (PMID 33805950, 2021). "In estrogen receptor (ER)-positive breast cancer, KDM6A protein is physically associated with ER and is necessary for the expression of hormone-response and proliferation-inducing genes." (PMID 33003334, 2020). "Whole exome sequencing (WES) detected multiple somatic variants in CTCs; some were in chromatin modeling factors KAT6B, KMT2D and KDM6A genes which are frequently mutated in breast cancer." (PMID 31003475, 2019). "Including Nigerian samples along with TCGA allowed us to identify PLK2, KDM6A, and B2M as novel significantly mutated genes in breast cancer, with the former two enriched in the HER2 + subtype." (PMID 30327465, 2018). "PLK2, KDM6A, and B2M are also identified as previously unreported significantly mutated genes in breast cancer." (PMID 30327465, 2018). "Consistent with this, a recent study linked the high expression of KDM6A to the proliferative capacity of breast cancer cell lines." (PMID 29029452, 2017). "While deposition of H3K27me3 by EZH2 enzyme is often increased in aggressive breast cancers, and mutation in the H3K27me3 demethylase KDM6A are common in renal cell carcinoma." (PMID 26840455, 2016). "Mutations in GRIN2A, GATA3 and KDM6A which have been identified in melanoma, breast cancer and recently identified as a candidate driver of pancreatic carcinogenesis, respectively, were only identified within the EUS FNA cytology smear specimens." (PMID 27203738, 2016). "H3K27 demethylase KDM6A up-regulated gene expression programs associated with growth and invasion of breast cancer cells." (PMID 26688070, 2015). "Indeed, treatment of KDM6A inhibitor GSK-J4 can repress various MET-associated genes in breast cancer cells." (PMID 33996581, 2021). "While KDM6A has been identified to exert tumor suppressive effects in several cancers, such as lung, hematologic, bladder, and breast cancer, it is noteworthy that KDM6A exhibits tumor-promoting activity in cervical cancer." (PMID 38791111, 2024). "Ubiquitously transcribed tetratricopeptide repeat, X chromosome (UTX)/KDM6A, as a highly mutated oncogene, has been described to be a histone demethylase in several cancers (pancreatic cancer, breast cancer, and acute myeloid leukemia)." (PMID 39707168, 2024). "For instance, Detection of epigenetic regulators, such as ZMYND8, E2F1 and KDM6A, would be beneficial for determining prognosis and management in breast cancer patients." (PMID 36967443, 2023). "The expression level of H3K27me3 demethylase, KDM6A, is reduced in a stem-like population of breast cancer cell lines." (PMID 35330189, 2022). "In breast cancer, KDM6A was determined to be a central in the mediation of epithelial-mesenchymal transition (EMT)." (PMID 35073341, 2022). "Similar to KDM4B, KDM6A is also induced by ERα and forms an ERα transcription activator in breast cancer during hormone stimulation." (PMID 35453496, 2022). "In breast cancer, it was identified that H3K27me3-demethylase KDM6A-mediated bivalent chromatin state functioned as a regulator of a series of EMT/MET-associated bivalent genes." (PMID 33996581, 2021). "KDM6A promotes the proliferation and migration of hormonally responsive breast cancer via feed-forward transcription with Erα." (PMID 34950587, 2021). "Recently, KDM6A has been shown to interact with CBP transcription-activator protein in a breast cancer cell-line MCF-7 in a Drosophila model." (PMID 33805950, 2021).
breast cancer (continued). "In invasive breast cancer cell lines, depletion of KDM6A leads to an increase in Myc-dependent EMT factors including SNAI1 and ZEB1/2." (PMID 33003334, 2020). "Our findings implicate KDM6A in the resolution of bivalency accompanying MET, and suggest KDM6A inhibition as a viable strategy to suppress metastasis formation in breast cancer." (PMID 29029452, 2017). "We also investigated the expression of KDM6A following TGFB-treatment of the E-cadherin+ve mouse mammary tumor cell line, 4T1." (PMID 29029452, 2017). "Furthermore, we discuss emerging therapeutic strategies for KMT2C-deficient breast cancers, such as epigenetic modulators (EZH2 inhibitors, KDM6A inhibitors, and BET inhibitors), DNA damage response (DDR)-targeting agents, and pathway-specific inhibitors." (PMID 41674102, 2026). "Also, KDM6A has been shown to interact directly with OCT4 to promote OCT4 target gene expression during chemotherapy in breast cancer cells." (PMID 39482699, 2024). "Inhibiting KDM6A/B with GSK-J4 has been shown to inhibit the proliferation of the luminal breast cancer cell lines MCF7 and MDA-MB-231, with the poorly differentiated triple-negative MDA-MB-231 cells showing greater resistance to the anti-proliferative effect of GSK-J4." (PMID 35915507, 2022). "However, KDM6A is suggested to play many different roles in the cell as 70% of KDM6A proteins were found to co-elute with smaller complexes in breast cancer cell lines." (PMID 35073341, 2022). "The H3K27me3-demethylase KDM6A, a bivalent chromatin regulator, served as the underlying mechanism of dynamic and reversible nature of EMT and MET in breast cancer cells, indicating that KDM6A may be a potential target to block the onset of MET." (PMID 33996581, 2021). "demonstrate that low expression of KDM6A predicts poor survival in breast cancer." (PMID 34950587, 2021). "In breast cancer, KDM6A is found to be an important factor in mediating EMT." (PMID 34950587, 2021). "However, later studies support an oncogenic role for KDM6A as it is overexpressed in breast cancer and correlates with cancer grades." (PMID 33003334, 2020). "There are divergent reports of KDM6A’s role in breast cancer." (PMID 33003334, 2020). "In breast cancer as well as others, the confusion concerning KDM6A’s role may be attributed to its suite of protein-protein interaction (KMT2D vs LSD1/HDAC1) or whether the activity is demethylase-dependent or demethylase-independent." (PMID 33003334, 2020). "Indeed, overexpression of the escape genes KDM5C, KDM6A and DDX3X is associated with cancer development, proliferation, invasion and metastasis in certain type of cancers such as breast cancer." (PMID 28686623, 2017). "However, the role of KDM6A in breast cancer remains controversy, and whether KDM6A can serve as a therapeutic target needs to be further investigated." (PMID 33868269, 2021). "Since we observed reduced KDM6A expression levels in cells that have undergone EMT and in stem cell-rich populations, we next sought to determine if breast cancer subtypes, enriched for EMT/CSC properties, also exhibit lower KDM6A levels." (PMID 29029452, 2017). "KDM6A physically interacts with ERα upon E2 treatment, demethylates H3K27me3 to facilitate the expression of C-X-C Motif Chemokine Receptor 4 (CXCR4) oncogene or the pluripotency factors NANOG, SOX2, and KLF4, which are related to breast cancer metastasis." (PMID 35453496, 2022). "The function of KDM6A is even different among subtypes of one disease, including acute myeloid leukemia, non-small cell lung cancer, squamous-like pancreatic cancer, T-cell acute lymphoblastic leukemia (T-ALL), breast cancer and glioblastoma." (PMID 34950587, 2021). "The authors showed that KDM6A directly interacts with the c-terminal region of MLL4 and the coordinated regulation of gene transcription by MLL4 and KDM6A promotes proliferation and invasion of breast cancer cells." (PMID 26688070, 2015).
breast cancer (continued). "Similarly, downregulation of neither Mmp3 nor Kdm6a had a significant effect on primary mammary tumour growth." (PMID 38926506, 2024). "In breast cancer, the MLL4-mediated H3K4me2 and the CBP/p300-c-Myc complex-mediated H3ac contribute to self-renewal of CSCs by regulating the expression of epithelial–mesenchymal transition (EMT) regulators, such as SNAIL, ZEB1, and ZEB2, in the absence of KDM6A." (PMID 33868269, 2021).
pancreatic cancer (31 papers, 2016 to 2025). "Several BET inhibitors have shown promise as adjuvant therapies in treating squamous-like and metastatic pancreatic cancers, particularly in KDM6A-deficient PDACs." (PMID 38791111, 2024). "In pancreatic cancer, loss of KDM6A leads to upregulation of CXCL1 expression, altering the immune microenvironment and recruiting tumor-associated neutrophils." (PMID 38840262, 2024). "KDM6A-deficient pancreatic cancer is sensitive to BET inhibitors (such as JQ1 and I-BET151), which can decrease the expression of SE-associated genes and suppress tumor growth." (PMID 36720920, 2023). "KDM6A loss was found to regulate aberrant activation of SEs of oncogenes, ultimately leading to pancreatic cancer development." (PMID 36720920, 2023). "Loss of function of KDM6A causes squamous-like metastatic pancreatic cancer through aberrant activation of super-enhancers at the loci of MYC and RUNX3 oncogenes and consequent MYC and RUNX3 over-expression." (PMID 38135679, 2023). "To address the question if the observed effects of Kdm6a are only applicable to liver tumours and only valid in the context of oncogenic c-myc, we additionally created a Kdm6a-deficient mouse model of pancreatic cancer." (PMID 34509979, 2022). "Strikingly, by expanding our murine studies to pancreatic cancer we also found the association between Kdm6a, Deptor and mTORC1 signalling, indicating that these observations are valid beyond liver cancer." (PMID 34509979, 2022). "Squamous cell, metastatic pancreatic cancer in females was also associated with loss of KDM6A expression in a knockout mouse model." (PMID 34220955, 2021). "KDM6A loss sensitizes pancreatic tumors to bromodomain and extra terminal (BET) domain inhibitors and histone deacetylase (HDAC) inhibitors." (PMID 33669845, 2021). "In mouse models, KDM6A loss induces squamous-like metastatic pancreatic cancer through aberrant activation of super-enhancers that regulate ΔNp63, c-MYC and RUNX." (PMID 33669845, 2021). "It was also reported to be lost or reduced in conjunction with KDM6A mutations in pancreatic cancers with squamous differentiation in male patients." (PMID 31201358, 2020). "More specifically, loss of the X-linked gene Lysine Demethylase 6A (KDM6A) resulted in a gender-specific aberrant activation of a set of enhancers leading to an aggressive phenotype of pancreatic cancer." (PMID 31067678, 2019). "KDM6A also plays a vital role in embryogenesis, and its mutations are found in human patients with pancreatic cancer." (PMID 31238554, 2019). "Another study found similar regions to be regulated by the histone demethylase KDM6A with loss of KDM6A resulting in sensitization of pancreatic cancer cells to bromodomain inhibitors." (PMID 31815011, 2019). "In pancreatic cancer, recent whole genomic sequencing also revealed pathogenic mutations and structural variants in several epigenetic regulator genes including KDM6A, ARID1A, ARID1B, PBRM1, SMARCA2, SMARCA4, and MLL2." (PMID 27999365, 2016). "Thus, Kdm6a is a potent tumour suppressor in pancreatic cancer and Kdm6a-deficient pancreatic adenocarcinomas show hyperactive mTORC1 signalling analogous to liver tumours." (PMID 34509979, 2022). "To examine the relationship between Hnf1a and Kdm6a deficiency in pancreatic cancer, we generated mice with pancreas‐specific inactivating Kdm6a mutations and oncogenic Kras mutations [Pdx1Cre, Kdm6aLoxP/LoxP, KrasG12D, hereafter referred to as Kdm6apKO;KrasG12D mice]." (PMID 32154941, 2020). "Moreover, in pancreatic cancer, KDM6A loss can be targeted using BETi through 78 small-molecule inhibitors." (PMID 31238554, 2019). "Hence, BET inhibitors like JQ1 may be useful for reversing the effects of KDM6A mutations in specific pancreatic cancer types." (PMID 38791111, 2024).
pancreatic cancer (continued). "Thus, BETi or HDACi may offer a synthetic lethality treatment strategy for pancreatic cancer upon KDM6A loss; in this subset of cancer cells, a correlation between loss of KDM6A expression and poor prognosis was observed." (PMID 31238554, 2019). "In pancreatic cancer, KDM6A inactivation leads to activation of super-enhancers, regulating tumor plasticity and making tumor cells more sensitive to BET inhibitors." (PMID 38840262, 2024). "As KDM6A plays an essential role in the differentiation, migration, and growth regulation of pancreatic cancer cells, deletion of this gene results in squamous differentiation, invasion, metastasis, and poor prognosis of PDAC." (PMID 38791111, 2024). "The BET inhibitor JQ1 is particularly effective in inhibiting squamous differentiation and controlling Kdm6a-null pancreatic cancer in vivo." (PMID 38791111, 2024). "In pancreatic cancer cells, reductions in KDM6A lead to the increased expression of activin A, a member of the transforming growth factor-β superfamily of cytokines that activates a noncanonical p38 MAPK pathway to induce mesenchymal identity and promote EMT." (PMID 36902253, 2023). "Treatment with BRD4 inhibitors results in KDM6A mutant pancreatic cancer cell differentiation and tumor growth inhibition in a mouse model." (PMID 38135679, 2023). "The transcriptional activator hepatocyte nuclear factor-1a (HNF-1a) is thought to be a key tumor suppressor in pancreatic cancer, and recruits KDM6A to indirectly inhibit the expression of genes involved in tumorigenesis and EMT." (PMID 36902253, 2023). "Here, we investigated the function of the histone demethylase KDM6A in gastrointestinal cancers, such as liver cancer and pancreatic cancer." (PMID 34509979, 2022). "Loss of KDM6A expression in female mice exhibited a squamous-like, malignant phenotype via activation of oncogenes MYC and RUNX3 in a pancreatic cancer mouse model." (PMID 34220955, 2021). "A study in pancreatic cancer found that concurrent loss of UTY and KDM6A in male patients was associated with a more malignant phenotype and poorer and prognosis." (PMID 34220955, 2021). "In the present review, we summarized the mutations of epigenetic regulators, including ARID1A, SMARCA2, SMARCA4, KDM6A, KMT2C, KMT2D, and BRD4 in GI cancers—in particular, pancreatic cancer—and found these regulators to be frequently mutated." (PMID 31238554, 2019). "The in vivo loss of KDM6A enhances gender-specific squamous-like pancreatic cancer, as an X-chromosomal gene via super-enhancer activation can be targeted with a BET inhibitor via KDM6A loss-regulated BRD4 function." (PMID 31238554, 2019). "The two most frequently altered histone methylation regulatory genes in pancreatic cancer are KDM6A and MLL2." (PMID 27999365, 2016). "Together, these data support the conclusion that the reduced expression of KDM6A may contribute to driving tumourigenesis in many, or perhaps most, pancreatic cancers." (PMID 40723241, 2025). "Mutations in the KDM6A gene, mostly deletions and truncations, are observed in 3–20% of PDAC samples, and the pancreatic-specific deletion of Kdm6a in mice leads to greatly accelerated Kras-driven pancreatic cancer." (PMID 40723241, 2025).